CRP (C-reactive protein)
Diseases named in the same sentence as CRP in open-access papers (continued):
Sharing a sentence is not in itself a finding about the gene and the disease.
Sepsis (continued). "Another report found that inflammation per se was the cause of fever in 57.7% of febrile AP patients and that prolonged fever of over 2 days was associated with higher severity, pancreatic necrosis, sepsis, and higher CT grades and CRP." (PMID 34797344, 2021). "Several biomarkers are associated with the occurrence and development of sepsis, such as LPS, IL-6, and CRP." (PMID 34281552, 2021). "The CRP*PCT has a high diagnostic value for sepsis patients, and other indicators can be used as an auxiliary diagnostic method for the death of sepsis patients’." (PMID 34233608, 2021). "Communication with clinicians revealed that the patient was on continuous UFH therapy and had an underlying sepsis, with highly elevated C-reactive protein (289 mg/L)." (PMID 34140837, 2021). "CRP has been widely used in clinical practice for sepsis, and it is associated with an increased risk of organ failure and death." (PMID 34429344, 2021). "Leukocytosis and acute phase biomarkers, such as fibrinogen and CRP were elevated, mirroring the intensity of inflammation and sepsis caused by the ischemic bowel." (PMID 35011941, 2021). "For an IG% above 6%, patients with > 60% TBSA or a CRP > 160 mg/L had a higher predicted sepsis risk that was near to or greater than 0.4, which was higher than the predictability of any single parameter alone." (PMID 34915849, 2021). "There are many causes for elevated CRP levels other than sepsis, including inflammation, burn injuries, cardiovascular disease, and malignancy, which all contribute to the low specificity and limited utility of CRP as a sepsis biomarker." (PMID 33198109, 2020). "Despite hs-CRP achieved remarkable specificity, it is associated with undesirable sensitivity, making it less ideal in early sepsis diagnosis." (PMID 33204274, 2020). "Critical values of acute-phase reactants typically associated with infections, including the C-reactive protein and procalcitonin, are also used to predict mortality of patients with general sepsis, with a moderate predictive power." (PMID 33267829, 2020). "Inflammatory markers such as procalcitonin and C-reactive protein have been proposed as both diagnostic and prognostic biomarkers in sepsis, although their performance in tropical Southeast Asia is inconsistent." (PMID 32605575, 2020). "MRproADM levels are significantly increased in patients with sepsis, but its diagnostic value for identifying sepsis is numerically lower than that of established markers (e.g., interleukin-6, C-reactive protein, and procalcitonin)." (PMID 32831638, 2020). "A low baseline glutamine level was associated with biochemical markers of sepsis (higher CRP and lower albumin values) and injury severity (higher APACHE II and SOFA scores)." (PMID 32028696, 2020). "Our study included large number of neonates with culture proven sepsis, clinical sepsis, and controls to correctly define the optimal cut-off values and measure the diagnostic performances of IL-6 and CRP." (PMID 33233806, 2020). "Forty biomarkers have been compared to PCT and/or CRP for their diagnostic value; 9 were shown to have a better diagnostic value for sepsis than either or both of these biomarkers." (PMID 32503670, 2020). "From the recent journal literature, it is known that COVID-19 infection is associated with the increased production of pro-inflammatory cytokines, C-reactive protein, increased risk of pneumonia, sepsis, acute respiratory distress syndrome, and heart failure." (PMID 32252338, 2020). "In the second regression results, these clinical characteristics plus PCT (OR: 1.143 (1.071-1.221)) and CRP (OR: 1.175 (1.081-1.277)) were independently associated with sepsis." (PMID 32802049, 2020). "NLR showed significant associations with all the tested lab parameters of sepsis, such as CRP (p = 0.02), procalcitonin (p < 0.01), and SOFA score (p = 0.01)." (PMID 33178505, 2020).
Sepsis (continued). "The NLR showed significant associations with all the tested lab parameters of sepsis, such as CRP (p = 0.02), procalcitonin (p = 0.01), and SOFA score (p = 0.01)." (PMID 33178505, 2020). "We recommend that CRP is considered as a useful diagnostic tool for inflammation or infection, but a less accurate prognostic one for sepsis." (PMID 32508526, 2020). "The present study showed that in incident ESRD patients, AF significantly associated with sepsis-related death and that CRP was associated with risk of mortality." (PMID 31999778, 2020). "The Z score was calculated for both sepsis groups; the results demonstrated that nCD64% achieved a higher score followed by hs-CRP as a univariant diagnostic sepsis biomarker." (PMID 32832553, 2020). "The diagnostic value of MRproADM for identifying sepsis is numerically lower than for established markers (CRP, PCT)." (PMID 32831638, 2020). "In a classical inflammatory state, such as sepsis and rheumatoid arthritis, serum Ang-2 levels are significantly increased and associated with C-reactive protein, which is a sensitive marker of inflammation." (PMID 32802878, 2020). "Multivariate regression analyses showed that previous clinical risk factors, PCT, and CRP were independent risk factors for postoperative sepsis." (PMID 32802049, 2020). "As alluded to previously, the only biomarkers that are currently included in the diagnostic workup of suspected sepsis are CRP and lactate." (PMID 32164268, 2020). "CRP is a risk factor for mortality in patients with sepsis when levels are elevated and the clearance rate is low." (PMID 32778146, 2020). "We also observed remarkable differences in the cut-off values and diagnostic performance of CRP in the first five days of serial measurements after neonates are suspected for sepsis." (PMID 33233806, 2020). "Low levels of albumin and high levels of sepsis-related biomarkers, including the C-reactive protein and lactate, were also significant risk factors for mortality." (PMID 33267829, 2020). "In 2017, we published a systematic review and meta-analysis of the diagnostic accuracy of presepsin in sepsis, which included subgroup analyses comparing to procalcitonin, and CRP." (PMID 33198109, 2020). "In the absence of methods for detecting the pathogenic bacterial agent, sepsis is diagnosed using clinical signs and increases in CRP concentrations." (PMID 32238170, 2020). "In further analyses, the diagnostic value of IL-6, sTREM-1, PCT, and CRP in the diagnosis of systemic inflammatory response syndrome and sepsis in feverish children was evaluated." (PMID 32655314, 2020). "Although MR-proANP levels were further elevated in critically ill patients with sepsis, their diagnostic power for sepsis was inferior to routinely used inflammatory markers such as CRP or procalcitonin." (PMID 31830996, 2019). "The most widely investigated diagnostic biomarkers for pediatric sepsis are C-reactive protein (CRP) and procalcitonin (PCT)." (PMID 31470804, 2019). "Currently available evidence indicates that presepsin has higher sensitivity and diagnostic accuracy, but lower specificity, than PCT or CRP in detecting sepsis in children." (PMID 31470804, 2019). "MRSA-mediated induction of the sepsis-associated molecule C-reactive protein (CRP), the proinflammatory cytokines IL-6, IL-1β, and TNF-α were also attenuated by Epi-1 treatment." (PMID 31835381, 2019). "Given the significance of multi-marker detection, we have devised a unique strategy to encompass the diagnostic value of PCT and CRP to identify sepsis at an early stage." (PMID 33117982, 2019). "In the present study, we evaluated the diagnostic and prognostic values of IL-6, PTX3, PCT, CRP, and lactate in patients with sepsis and septic shock diagnosed using Sepsis-3 definitions." (PMID 31718563, 2019).
Sepsis (continued). "In a multivariate logistic regression analysis with CTRP1 and these parameters to test its association with sepsis, only CRP remained an independent and highly significant predictor of sepsis." (PMID 31083558, 2019). "The aims of the present meta-analysis were to assess the overall diagnostic accuracy of presepsin in pediatric sepsis and compare it to those for C-reactive protein (CRP) and procalcitonin (PCT)." (PMID 31470804, 2019). "A total of 1,110 patients diagnosed with sepsis were retrospectively analyzed to identify response patterns for risk stratification of routine parameters measured at the peak level of C-reactive protein." (PMID 31275752, 2019). "Noteworthy, elevated NT-proBNP has been associated with an almost sevenfold higher risk of mortality in sepsis and is a predictor of survival when compared to traditional biomarkers of sepsis including C-reactive protein and procalcitonin." (PMID 31234943, 2019). "Univariate analysis of the association between CRP levels and parasitemia, malaria and septicemia in 548 patient visits." (PMID 30080904, 2018). "Most studies investigating the potential association between RMR and CRP were performed in severely ill patients, such as those suffering from chronic kidney disease, sepsis, or pancreatic cancer." (PMID 30294302, 2018). "These previous studies have reported that the CRP/ALB ratio measured on admission was an independent risk factor in patients with severe sepsis or septic shock." (PMID 29495423, 2018). "This study focused on the use of CRP as an adjunctive diagnostic tool in the evaluation of VLBW infants with suspected late-onset sepsis." (PMID 29382319, 2018). "Unlike PV or PsA, GPP is associated with a generalized erythematous flush and sepsis-like systemic symptoms, including high fever, leukocytosis, and elevated CRP levels." (PMID 30647802, 2018). "Contemporary data suggests that sepsis-induced immunosuppression is linked to persistent inflammation with elevated CRP levels and neutrophil counts along with presence of lymphocytopenia and immature myeloid suppressor cells in peripheral blood." (PMID 29466395, 2018). "CRP levels have been shown to be associated with various conditions, including severe sepsis, heart failure, cerebral disease, and other inflammatory diseases." (PMID 30297655, 2018). "Multivariate analysis of the association between CRP levels and other parameters, and parasitemia, malaria and septicemia in 548 patient visits." (PMID 30080904, 2018). "A previous review revealed that CRP performs relatively inaccurately in the diagnostic tasks of sepsis compared with PCT." (PMID 28875483, 2017). "In the present study, we have investigated the diagnostic value of known biomarkers, i.e., PCT, the NLCR, CRP and lactate, alone as well as in combination using a large sample consisting of 1,572 episodes of adult patients suspected with sepsis." (PMID 28727802, 2017). "The induction of sepsis-associated blood C-reactive protein (CRP) and the pro-inflammatory cytokine IL-6 in response to MRSA infection was also suppressed in pigs that received Epi-1." (PMID 28177877, 2017). "Although CRP is another commonly used biomarker in the clinical context, previous studies revealed that its diagnostic accuracy for sepsis is significantly lower than PCT." (PMID 28875483, 2017). "In the last guideline, increase in CRP levels by 2 standard deviation (SD) is defined as a diagnostic criteria for sepsis." (PMID 26863002, 2016). "Other studies have suggested inflammatory processes as a risk factor for AF, with SIRS, sepsis and a raised C reactive protein being implicated." (PMID 27038791, 2016). "Recent studies have shown that rs2229094 was associated with type 2 diabetes, CRP levels, sepsis, Crohn’s disease, and cancer risk." (PMID 26999109, 2016).
Sepsis (continued). "This study established that APACHE II score (≥14.5), CRP (≥34.25 mg/L), and blood lactate (≥2.35 mmol/L) were the independent risk factors of hypoalbuminemia in the early stage of surgical sepsis." (PMID 26557421, 2015). "Panels of biomarkers, including sTREM-1, procalcitonin, CD 64 expression on neutrophils, and C-reactive protein, as well as other novel biomarkers, offers some promise as diagnostic markers of sepsis yet to be confirmed in large scale clinical trials." (PMID 25927426, 2015). "Considering the high morbidity and mortality associated with it, clinical criteria along with other hematological parameters and diagnostic markers along with serial CRP should be considered in evaluating a neonate for sepsis." (PMID 26150837, 2015). "The aim of this study was to compare the diagnostic ability of this universal assay with CRP and blood culture for the diagnosis of late onset sepsis in VLBW infants." (PMID 26305781, 2015). "In this study, patients in the high CRP group treated with inappropriate antibiotics in the first 24 h were at especially higher risk of infectious complications and sepsis attributable mortality." (PMID 26259626, 2015). "A similar association between elevated CRP levels and mortality has been observed in neonates hospitalized with sepsis." (PMID 25909192, 2015). "CRP has been suggested to predict therapeutic response and outcome in sepsis, and slower changes have been associated with persistent infection, organ failure, or mortality in the intensive care unit (ICU)." (PMID 26367532, 2015). "Severe sepsis during the first 48 hours was independently associated with IE, as well as high levels of C-reactive protein." (PMID 26020939, 2015). "In conclusion, APACHE II score (≥14.5), CRP (≥34.25 mg/L), and blood lactate (≥.35 mmol/L) were established as the independent risk factors of hypoalbuminemia in the early stage of surgical sepsis." (PMID 26557421, 2015). "Initial lactate level, lactate clearance, C-reactive protein, and procalcitonin in critically ill patients with sepsis are associated with hospital mortality." (PMID 26692209, 2015). "Association between time-dependent ferritin and all-cause mortality and cardiovascular or sepsis-related mortality in patients with C-reactive protein <0.5 mg/dL and ≧0.5 mg/dL during follow-up using time-dependent Cox proportional hazards models." (PMID 25462819, 2014). "High MMP-8 and low MMP-9, which correlated with plasma CRP levels, were associated with sepsis, in addition to high fibrinogen levels and neutrophils counts." (PMID 24833564, 2014). "Elevated CRP levels in sepsis have been correlated with increased risk of death and organ failure, but in part due to the persistence of elevated levels, were unable to predict survival when evaluating CRP trends." (PMID 24772418, 2014). "We found decreased all-cause mortality and a trend to decreased cardiovascular and sepsis-related mortality in patients with normal CRP levels." (PMID 25462819, 2014). "Early neutrophil, but not lymphocyte or monocyte, CD64 expression differentiates children with sepsis from those with trauma and is associated with high CRP, PCT." (PMID 23452299, 2013). "Sepsis (CRP 93) was identified as a plausible causative factor behind the sudden deterioration, even if no agent was identified with virological as well as bacteriological blood culturing (case 17)." (PMID 23551812, 2013). "The implementation of a computerized CRP-based early sepsis evaluation protocol for VLBW infants was associated with a reduction of antimicrobial days/doses without evidence of increased risk in infants treated per the algorithm." (PMID 24244325, 2013). "The purpose of this study was to investigate the value of PCT and C-reactive protein (CRP) as diagnostic markers of sepsis and to evaluate the prognostic value of these markers related to the severity of injury, sepsis and mortality." (PMID 24330775, 2013).
Sepsis (continued). "When repeating the analysis excluding the 1,157 participants with unadjudicated potential sepsis events, there was a similar association between CRP and incident sepsis (adjusted HR 1.51; 95% CI 1.31–1.76)." (PMID 23935961, 2013). "After adjusting for the Simplified Acute Physiology Score II and severity of sepsis, CRP time course was significantly associated with ICU mortality (OR = 1.03, CI 95% 1.02–1.04, P < 0.001)." (PMID 24286072, 2013). "Authors have suggested that CRP can be used both as a diagnostic tool for sepsis and as a guide when evaluating treatment efficacy in infected patients." (PMID 23555017, 2013). "The objective of this study was to determine the association between baseline high-sensitivity CRP (hsCRP) and future risk of sepsis in community-dwelling individuals." (PMID 23935961, 2013). "The primary aim of this study is to examine the association between CRP gene polymorphism and serum levels of CRP in correlation with early onset sepsis (EOS) infection in newborns." (PMID 23941472, 2013). "In stage II NEC, CRP levels that remained elevated for more than 9 days were associated with the development of stricture or secondary sepsis, such as peritonitis or intra-abdominal abscess." (PMID 24146936, 2013). "The primary aim of this study is to examine the association between CRP gene polymorphism and serum levels of CRP in correlation with early onset sepsis (EOS) infection in newborns living in Taif city, Saudi Arabia." (PMID 23941472, 2013). "The results obtained in this study (combined study group) have shown higher levels of CRP associated with A-allele carriers (high producer allele) of the CRP-286 (C>T>A) in symptomatic group compared to sepsis free controls." (PMID 23941472, 2013). "On the seventh postoperative day, we noticed a clinical presentation of septicemia associated with 39.8°C hyperthermia, a white blood cell count of 15 × 109/L and a CRP level increased by 114mg/L." (PMID 23098279, 2012). "In our study the 3rd day SOFA score and the 3rd day CRP value were shown to be risk indicators for sepsis related mortality when comparing severity scores." (PMID 23171626, 2012). "A meta analysis of 33 studies, which included adults in intensive care units or after surgery and trauma, showed that PCT was a good diagnostic marker of sepsis, with greater diagnostic accuracy than CRP." (PMID 23275327, 2012). "Our review showed suPAR to have low diagnostic value in patients with SIRS, bacteremia, or sepsis, even lower than CRP, PCT, and sTREM-1." (PMID 22706919, 2012). "The risk of sepsis related mortality appears to be increased when the 3rd day CRP value is greater than 100 mg/dL." (PMID 23171626, 2012). "Some studies suggested that increased CRP level was associated with sepsis and mortality of critical illness." (PMID 21714897, 2011). "After adjusting for the Simplified Acute Physiology Score II and severity of sepsis, the CRP course was significantly associated with mortality (ORCRP-ratio = 1.03, confidence interval 95%= (1.02, 1.04), P < 0.001)." (PMID 21762483, 2011). "After adjusting for SAPS II and severity of sepsis, the pattern of CRP-ratio response remained significantly associated with mortality." (PMID 21762483, 2011). "Dornbusch and colleagues, in a small retrospective study, evaluated the diagnostic value of PCT and CRP in differentiating sepsis and febrile reaction after administration of anti-T-lymphocyte antibodies in pediatric patients." (PMID 19291300, 2009). "In our patients, elevated CRP, S-100β, and cortisol were associated with sepsis-associated delirium." (PMID 18457586, 2008). "Following the overall dynamics of CRP, blood levels can improve the prognostic and diagnostic value of CRP as a marker of sepsis severity compared with consideration of its values separately at single time points." (PMID 17598889, 2007).